RNU1-143P (RNA, U1 small nuclear 143, pseudogene)
Gene: Small nuclear RNA gene on chromosome 1 (143,791,542 to 143,791,687, reverse strand). Ensembl gene ENSG00000252105.
Homologues: Orthologues: chimpanzee U1 (100% identical), macaque U1 (91% identical), dog U1 (71% identical), guinea pig U1 (64% identical). Paralogues in human: RNU1-153P (100% identical), RNU1-68P (100% identical), U1 (100% identical), RNU1-5P (94% identical), U1 (92% identical), RNU1-6P (90% identical), RNU1-1 (75% identical), RNU1-19P (75% identical), RNU1-2 (75% identical), RNU1-27P (75% identical), RNU1-28P (75% identical), RNU1-3 (75% identical), and 134 more.